GARRE1 (granule associated Rac and RHOG effector 1)
Description:
Acts as an effector of RAC1. Associates with CCR4-NOT complex which is one of the major cellular mRNA deadenylases and is linked to various cellular processes including bulk mRNA degradation, miRNA-mediated repression, translational repression during translational initiation and general transcription regulation. May also play a role in miRNA silencing machinery.
Synonyms: KIAA0355; MiniBAR
Tractability: PROTAC: ubiquitination databases record sites on it.
Gene: Protein-coding gene on chromosome 19 (34,254,543 to 34,355,566, forward strand). Ensembl gene ENSG00000166398.
Subcellular location: Cytoplasm, P-body
Subcellular location (Human Protein Atlas): Nucleoplasm
Pathways (Reactome):
Signal Transduction: RAC1 GTPase cycle; RAC2 GTPase cycle; RAC3 GTPase cycle; RHOG GTPase cycle
Gene Ontology:
Molecular function: CCR4-NOT complex binding; protein binding; small GTPase binding
Biological process: Rac protein signal transduction
Cellular component: P-body; cytosol
Genetic constraint (gnomAD): Loss-of-function variants: 44 observed, 97.65 expected, observed/expected ratio (o/e) 0.45, 90% interval 0.35 to 0.58. The upper end of that interval is the gene's LOEUF score, 0.58, which puts it in group 2 of 6, group 1 being the genes least tolerant of losing a copy. Missense variants: 1,184 observed, 1,382.4 expected, observed/expected ratio (o/e) 0.86, 90% interval 0.82 to 0.9. Synonymous variants: 500 observed, 538.22 expected, observed/expected ratio (o/e) 0.93, 90% interval 0.86 to 1.
Homologues: Orthologues: chimpanzee GARRE1 (99% identical), macaque GARRE1 (99% identical), dog GARRE1 (96% identical), rabbit GARRE1 (95% identical), pig GARRE1 (95% identical), guinea pig GARRE1 (94% identical), mouse Garre1 (93% identical), rat Garre1 (93% identical), tropical clawed frog garre1 (74% identical), zebrafish GARRE1 (65% identical), zebrafish garre1 (14% identical).
Diseases named in the same sentence as GARRE1 in open-access papers:
GARRE1 is named in the same sentence as 1 disease in open-access papers, as found by Europe PMC text mining. Sharing a sentence is not in itself a finding about the gene and the disease.
GARRE1 shares sentences with these, for which no sentence is quoted: intervertebral disc disease (3 papers).